OTULIN (OTU deubiquitinase with linear linkage specificity)
Description:
Deubiquitinase that specifically removes linear ('Met-1'-linked) polyubiquitin chains to substrates and acts as a regulator of angiogenesis and innate immune response. Required during angiogenesis, craniofacial and neuronal development by regulating the canonical Wnt signaling together with the LUBAC complex. Acts as a negative regulator of NF-kappa-B by regulating the activity of the LUBAC complex. OTULIN function is mainly restricted to homeostasis of the LUBAC complex: acts by removing 'Met-1'-linked autoubiquitination of the LUBAC complex, thereby preventing inactivation of the LUBAC complex. Acts as a key negative regulator of inflammation by restricting spontaneous inflammation and maintaining immune homeostasis. In myeloid cell, required to prevent unwarranted secretion of cytokines leading to inflammation and autoimmunity by restricting linear polyubiquitin formation. Plays a role in innate immune response by restricting linear polyubiquitin formation on LUBAC complex in response to NOD2 stimulation, probably to limit NOD2-dependent pro-inflammatory signaling.
Synonyms: FAM105B; FLJ34884; AIPDS; AIPDSA; GUM; IMD107
Tractability: PROTAC: UniProt records ubiquitination sites on it; ubiquitination databases record sites on it; its protein half-life has been measured.
Gene: Protein-coding gene on chromosome 5 (14,664,664 to 14,716,529, forward strand). Ensembl gene ENSG00000154124.
Subcellular location: Cytoplasm
Subcellular location (Human Protein Atlas): Mitochondria; Plasma membrane
Pathways (Reactome):
Metabolism of proteins: Synthesis of active ubiquitin: roles of E1 and E2 enzymes
Signal Transduction: Regulation of TNFR1 signaling
Gene Ontology:
Molecular function: cysteine-type deubiquitinase activity; cysteine-type peptidase activity; protein binding
Biological process: innate immune response; negative regulation of inflammatory response; nucleotide-binding oligomerization domain containing 2 signaling pathway; protein linear deubiquitination; regulation of tumor necrosis factor-mediated signaling pathway; protein ubiquitination; regulation of canonical Wnt signaling pathway; sprouting angiogenesis
Cellular component: cytoplasm; cytosol; LUBAC complex
Genetic constraint (gnomAD): Loss-of-function variants: 15 observed, 34.65 expected, observed/expected ratio (o/e) 0.43, 90% interval 0.29 to 0.67. The upper end of that interval is the gene's LOEUF score, 0.67, which puts it in group 2 of 6, group 1 being the genes least tolerant of losing a copy. Missense variants: 312 observed, 431.46 expected, observed/expected ratio (o/e) 0.72, 90% interval 0.66 to 0.79. Synonymous variants: 154 observed, 167.97 expected, observed/expected ratio (o/e) 0.92, 90% interval 0.8 to 1.05.
Homologues: Orthologues: chimpanzee OTULIN (99% identical), macaque OTULIN (97% identical), pig OTULIN (91% identical), dog OTULIN (90% identical), mouse Otulin (90% identical), rat Otulin (88% identical), guinea pig OTULIN (86% identical), rabbit OTULIN (86% identical), tropical clawed frog otulin (55% identical), zebrafish otulinb (40% identical). Paralogues in human: OTULINL (33% identical).
Diseases named in the same sentence as OTULIN in open-access papers:
OTULIN is named in the same sentence as 60 diseases in open-access papers, as found by Europe PMC text mining. Sharing a sentence is not in itself a finding about the gene and the disease. The quoted sentences say what the papers report.
OTULIN-related autoinflammatory syndrome (22 papers, 2016 to 2026). "Clinical signs of otulipenia, a recently identified autoinflammatory condition caused by loss-of- function mutations in OTULIN, the gene encoding a deubiquitinase that cleaves Met1-linked chains, include skin lesions and fat loss." (PMID 41466885, 2026). "Patients carrying biallelic, deleterious mutations of OTULIN suffer from a neonatal onset, severe autoinflammatory disorder known as OTULIN-related autoinflammatory syndrome (ORAS)." (PMID 41293556, 2025). "In both humans and mice, loss-of-function mutations in OTULIN lead to the development of an autoinflammatory disease known as OTULIN-related autoinflammatory syndrome (ORAS)." (PMID 41446873, 2025). "Genetic mutations in OTULIN cause the development of OTULIN-related autoinflammatory syndrome (ORAS), which is associated with recurrent fevers, autoantibodies, diarrhea, panniculitis, and arthritis." (PMID 38017534, 2023). "Limiting TNF-based pro-inflammatory responses also improves symptoms in patients homozygous for rare variants in OTULIN and suffering from an autoinflammatory syndrome called OTULIN-related autoinflammatory syndrome or otulipenia." (PMID 37589075, 2023). "In the same year, another group identified three more patients, from three different consanguineous families, carrying OTULIN biallelic mutations and symptoms of systemic sterile inflammation (e.g., prolonged fevers and diarrhoea) that they called Otulipenia." (PMID 35740456, 2022). "Autosomal recessive hypomorphic loss-of-function mutations of OTULIN have been linked to an early-onset severe inflammatory disease, named OTULIN-related autoinflammatory syndrome (ORAS, also named Otulipenia)." (PMID 34434197, 2021). "In humans, OTULIN deficiency results in development of OTULIN-related autoinflammatory syndrome (ORAS), which is associated with recurrent fevers, autoantibodies, diarrhea, panniculitis, and arthritis." (PMID 34685685, 2021). "Recessively inherited loss-of-function mutations in OTULIN caused patients to have an early onset severe autoinflammatory disease termed otulipenia/ORAS (OTULIN-related autoinflammatory syndrome)." (PMID 29544517, 2018). "Fat loss and skin lesions are clinical manifestations of a recently described autoinflammatory syndrome named otulipenia, due to loss-of-function mutations in OTULIN, encoding a deubiquitinase that cleaves Met1-linked chains." (PMID 28848544, 2017). "Recessively inherited loss-of-function mutations in the linear (Met1)-specific DUB OTULIN have been linked to the early-onset severe inflammatory disease, named otulipenia/ORAS." (PMID 28469620, 2017). "A homozygous hypomorphic mutation in human OTULIN causes a potentially fatal autoinflammatory condition termed OTULIN-related autoinflammatory syndrome (ORAS)." (PMID 27523608, 2016). "Moreover, homozygous or compound heterozygous OTULIN variants cause an autoinflammatory disease called otulipenia or OTULIN-related autoinflammatory syndrome (ORAS) in an autosomal recessive fashion." (PMID 38652464, 2024). "This study describes an OTULIN-related autoinflammatory syndrome (ORAS) patient with two rare heterozygous variants of OTULIN (p.P152L and p.R306Q); the latter is a de novo variant that acts in a dominant-negative manner to cause ORAS." (PMID 38652464, 2024). "OTULIN-related autoinflammatory syndrome (ORAS), a severe autoinflammatory disease, is caused by biallelic pathogenic variants of OTULIN, a linear ubiquitin-specific deubiquitinating enzyme." (PMID 38652464, 2024). "The deubiquitinase OTULIN negatively regulates M1-linked polyubiquitin signalling by removing the chains conjugated by LUBAC, and OTULIN deficiency causes OTULIN-related autoinflammatory syndrome (ORAS) in humans." (PMID 32231246, 2020). "The OTULIN-mutant mouse models were extremely useful to unveil the link between OTULIN mutations and excessive linear chains in ORAS/Otulipenia." (PMID 35740456, 2022).
OTULIN-related autoinflammatory syndrome (continued). "OTULIN is related to inflammatory disease, which is known as OTULIN-related auto-inflammatory syndrome (ORAS)." (PMID 33919439, 2021). "OTULIN-related autoinflammatory syndrome (ORAS), also known as otulipenia, is an autoinflammatory disease caused by biallelic LoF mutations in the linear deubiquitinase OTULIN." (PMID 34163478, 2021). "Here, we describe that a homozygous hypomorphic OTULIN mutation in a consanguineous family causes a potentially fatal autoinflammatory disorder termed OTULIN-related autoinflammatory syndrome (ORAS), which can be managed by Infliximab (anti-TNF neutralizing antibody)." (PMID 27523608, 2016). "Interestingly, homozygous loss-of-function mutations in the OTULIN gene cause an auto-inflammatory condition, called ORAS (OTULIN-related inflammatory syndrome) or otulipenia that is responsive to anti-TNF treatment." (PMID 31998699, 2019). "Otulipenia, also known as OTULIN-related autoinflammatory syndrome (ORAS), is an autosomal recessive autoinflammatory disease due to mutations in the FAM105B gene, which encodes OTULIN, a Met-1 specific deubiquitinase that acts as a negative regulator of the NF-κB signaling pathway." (PMID 31736939, 2019).
autoinflammatory syndrome (16 papers, 2017 to 2024). A group of disorders of the innate immune system characterized by attacks of seemingly unprovoked inflammation without significant levels of either autoantibodies or autoreactive T cells more characteristic of autoimmune disease. "Homozygous hypomorphic mutations in the human OTULIN gene, affecting the deubiquitinase activity of the protein, have been shown to underlie the development of a severe life-threatening autoinflammatory syndrome, called ORAS15,16." (PMID 34625556, 2021). "Most recently, it was demonstrated that haploinsufficiency of OTULIN due to heterozygous variants was associated with an increased risk of life-threatening necrosis upon staphylococcal infection, while complete OTULIN deficiency causes an auto-inflammatory syndrome." (PMID 35986347, 2022). "Clinically, OTULIN loss of function leads to OTULIN-related autoinflammatory syndrome." (PMID 35939695, 2022). "Germline mutations in OTULIN that destabilises OTULIN and/or interfere with its activity, cause an early onset autoinflammatory syndrome (termed OTULIN-related autoinflammatory syndrome) characterised by recurrent fevers, diarrhoea, panniculitis, autoantibodies and arthritis." (PMID 33473179, 2021). "Conditional deletion of OTULIN in myeloid cells leads to accumulation of Met1-linked ubiquitin chains, constitutive NF-κB activation and chronic inflammation as well as autoimmunity resembling the human ORAS (OTULIN—related auto-inflammatory syndrome) caused by hypomorphic OTULIN germline mutations." (PMID 31541095, 2019). "Finally, expression of a hypomorphic mutant Otulin allele, previously shown to cause OTULIN-related autoinflammatory syndrome in humans, induces a similar inflammatory phenotype, thus supporting the importance of OTULIN for restraining skin inflammation and maintaining immune homeostasis." (PMID 34625556, 2021). "Homozygous mutation in the OTULIN gene is causative for AIPDS-autoinflammation, panniculitis, and dermatosis syndrome (OMIM, #617099) alternatively referred to as ORAS-OTULIN-related autoinflammatory syndrome." (PMID 37569318, 2023). "In humans, OTULIN deficiency causes a severe autoinflammatory syndrome, ORAS, and genetic ablation of OTULIN in immune cells in mice replicate many inflammatory hallmarks of ORAS." (PMID 32231246, 2020). "Importantly, patients carrying loss-of-function mutations in the OTULIN gene suffer from ORAS (OTULIN-related autoinflammatory syndrome), a severe and often lethal autoinflammatory syndrome affecting multiple organs including skin." (PMID 38649745, 2024). "The deubiquitinase OTULIN removes methionine‐1 (M1)‐linked polyubiquitin signals conjugated by the linear ubiquitin chain assembly complex (LUBAC) and is critical for preventing TNF‐driven inflammation in OTULIN‐related autoinflammatory syndrome (ORAS)." (PMID 30804083, 2019). "For the negative role of OTULIN in immune responses, OTULIN deficiency might cause auto-inflammatory syndrome." (PMID 32650621, 2020).
ovarian tumor (7 papers, 2014 to 2023). "The ovarian tumor (OTU) family DUB OTULIN (FAM105B) exclusively cleaves linear (Met1-linked) poly-ubiquitin chains and plays important roles in auto-immunity, inflammation and infection." (PMID 33288901, 2021). "OTULIN (OTU domain DUB with Linear Linkage specificity), also known as Gumby/FAM105b, is a member of the ovarian tumor-associated protease family (OTUs) and it is a deubiquitinating enzyme that specifically hydrolyzes Met1-Ub linear linkages." (PMID 33498168, 2021). "The OTULIN, encoded by FAM105B, comprises of ovarian tumor (OUT) domain and PUB interacting motif (PIM) domain." (PMID 37813853, 2023). "As a new member of the ovarian tumor (OTU) domain family, the deubiquitinase OTULIN was reported to be involved in acute systemic inflammation, chronic inflammation and autoimmunity via regulating the NF-κB pathway." (PMID 29544517, 2018). "To evaluate the selectivity of OTULIN ABP for OTULIN, we first tested its reactivity in vitro against a panel of DUBs from the OTU (ovarian tumor), USP, and UCH (ubiquitin C-terminal hydrolases) families." (PMID 28919039, 2017). "To test this hypothesis we performed SRLM on U2OS cells transfected with plasmids expressing the de-ubiquitinases (DUBs) CYLD, (cylandromatosis DUB) or OTULIN (ovarian tumour DUB with linear linkage specificity; also known as FAM105B)." (PMID 27586688, 2016).
panniculitis (7 papers, 2016 to 2023). Inflammation of the subcutaneous adipose tissue. "Patients with homozygous loss‐of‐function variants in the OTU‐deubiquitinase OTULIN suffer from neonatal‐onset OTULIN‐related autoinflammatory syndrome (ORAS) characterized by fever, panniculitis, diarrhea, and arthritis." (PMID 35170849, 2022). "For example, ORAS patients suffer from panniculitis, and it will be informative to study the role of OTULIN in skin homeostasis and inflammation." (PMID 27523608, 2016). "To study how OTULIN mutations impact on non‐haematopoietic cells and how these cells may contribute to the clinical aspects of ORAS, e.g. panniculitis, we established a primary dermal fibroblast culture from patient III." (PMID 30804083, 2019).
Autoimmunity (6 papers, 2016 to 2024). The occurrence of an immune reaction against the organism's own cells or tissues. "Targeted deletion of OTULIN in myeloid cells caused chronic inflammation and autoimmunity by amplifying NF-κB activity." (PMID 29544517, 2018). "To understand how OTULIN deficiency caused autoinflammation and autoimmunity, we attempted to recapitulate ORAS in mouse models." (PMID 27523608, 2016). "Importantly, loss of function of OTULIN drives inflammation and autoimmunity in mice and leads to OTULIN‐related autoinflammatory syndrome (ORAS) in humans." (PMID 33324551, 2020). "We conclude that loss of OTULIN function and increased levels of M1-linked polyUb in human cells may indeed lead to the severe inflammation and autoimmunity observed in ORAS." (PMID 27523608, 2016). "In addition, loss of OTULIN in myeloid cells generates a chronic model in which mice display increased serum levels of inflammation-associated cytokines and chemokines and develop splenomegaly and autoimmunity." (PMID 27523608, 2016). "LOF variants in genes that negatively regulate the activation of NF-κB, such as those encoding deubiquitinases OTULIN or TNFAIP3/A20, lead to uncontrolled inflammation, autoimmunity, and autoinflammatory diseases." (PMID 38593810, 2024). "Together, the data from mouse models and human patients clearly establish OTULIN and M1-linked polyUb chains as key regulators of immune homeostasis, inflammation, and autoimmunity and reveal cell-type-specific effects of OTULIN in immune cells." (PMID 27523608, 2016). "Collectively, these results show that OTULIN is essential in myeloid cells to prevent unwarranted secretion of cytokines leading to inflammation, as well as autoimmunity." (PMID 27523608, 2016).
breast carcinoma (6 papers, 2020 to 2023). "In the human MDA-MB-231 breast cancer cell model, OTULIN loss caused deficits in Wnt5a-induced filopodia extension and trafficking of transfected HA-VANGL2." (PMID 37589075, 2023). "Increased OTULIN levels are associated with aggressive molecular subtypes and poor survival in breast cancer patients." (PMID 32770022, 2020). "We further show that increased OTULIN levels are associated with aggressive breast cancer subtypes and correlate with poor survival in breast cancer patients." (PMID 32770022, 2020). "Finally, we found that in the MDA-MB-231 breast cancer cell model for Wnt5a signaling, OTULIN loss led to deficits in Wnt5a-induced filopodia extension and redistribution of transfected HA-VANGL2." (PMID 37589075, 2023). "This OTULIN phosphorylation promotes genotoxic Wnt/β-catenin activation and enhances drug resistance in breast cancers." (PMID 38017534, 2023). "Because MDA-MB-231 breast cancer cells are an established cell culture system used to study responses to PCP ligands, such as Wnt5a, we examined the consequences of OTULIN loss on Wnt5a responses in these cells." (PMID 37589075, 2023). "OTULIN-mediated Wnt/β-catenin activation promotes metastasis and drug resistance of breast cancer cells." (PMID 37311739, 2023). "Analyzing OTULIN transcription levels in TCGA-BRCA genomic dataset revealed that OTULIN expression is significantly higher in the basal-like subtype of breast cancer than that in other molecular subtypes." (PMID 32770022, 2020). "To further validate the role of OTULIN-mediated Wnt activation in promoting breast cancer drug resistance in vivo, we established orthotopic TNBC xenograft models with WT or OTULIN-KO MDA-MB-231 LM2 cells." (PMID 32770022, 2020). "As in a recently published paper, transcriptomic analysis based on the TCGA-BRCA genomic dataset showed significantly higher mRNA levels of OTULIN in the BL subtype of breast cancer than that in other molecular subtypes (i.e., HER2+, luminal A, luminal B, and normal subtypes)." (PMID 35939695, 2022). "Thus, OTULIN-mediated Wnt/β-catenin activation upon genotoxic treatments promotes drug resistance and metastasis in breast cancers." (PMID 32770022, 2020). "Importantly, high OTULIN levels are associated with shorter OS and DFS in breast cancer patients." (PMID 32770022, 2020). "All these data support that increased OTULIN levels strongly correlated with upregulated Wnt/β-catenin signaling and TNBC/basal-like molecular subtypes in breast cancer patients." (PMID 32770022, 2020). "Remarkably, the reciprocally changed levels of OTULIN and HOIP revealed from these small sets of TNBC specimens were also reflected in large cohorts of breast cancer specimens; no significant change in CYLD protein expression was shown." (PMID 35939695, 2022).